FAM13B (family with sequence similarity 13 member B)
Synonyms: C5orf5; FAM13B1; N61; KHCHP; ARHGAP49
Tractability: No criterion of Open Targets' tractability assessment is met for any kind of drug.
Gene: Protein-coding gene on chromosome 5 (137,937,960 to 138,051,961, reverse strand). Ensembl gene ENSG00000031003.
Subcellular location (Human Protein Atlas): Nucleoplasm
Pathways (Reactome):
Signal Transduction: CDC42 GTPase cycle; RAC1 GTPase cycle
Gene Ontology:
Molecular function: GTPase activator activity
Biological process: regulation of small GTPase mediated signal transduction; signal transduction
Cellular component: cytosol
Genetic constraint (gnomAD): Loss-of-function variants: 44 observed, 96.61 expected, observed/expected ratio (o/e) 0.46, 90% interval 0.36 to 0.59. The upper end of that interval is the gene's LOEUF score, 0.59, which puts it in group 2 of 6, group 1 being the genes least tolerant of losing a copy. Missense variants: 860 observed, 993.58 expected, observed/expected ratio (o/e) 0.87, 90% interval 0.82 to 0.92. Synonymous variants: 300 observed, 325.79 expected, observed/expected ratio (o/e) 0.92, 90% interval 0.84 to 1.01.
Homologues: Orthologues: chimpanzee FAM13B (99% identical), macaque FAM13B (99% identical), dog FAM13B (95% identical), pig FAM13B (93% identical), rabbit FAM13B (92% identical), guinea pig FAM13B (91% identical), rat Fam13b (83% identical), mouse Fam13b (82% identical), tropical clawed frog fam13b (57% identical), zebrafish fam13b (35% identical), Drosophila melanogaster CG6424 (19% identical). Paralogues in human: FAM13A (42% identical), FAM13C (21% identical).
Diseases named in the same sentence as FAM13B in open-access papers:
FAM13B is named in the same sentence as 15 diseases in open-access papers, as found by Europe PMC text mining. Sharing a sentence is not in itself a finding about the gene and the disease. The quoted sentences say what the papers report.
myocardial infarction (1 paper, 2025). Gross necrosis of the myocardium, as a result of interruption of the blood supply to the area, as in coronary thrombosis. "After Bonferroni correction, the results revealed that, with the exception of the FAM13B gene (no corresponding data available) and the LIPA gene (unstable causal relationship with MI), the remaining 11 genes all demonstrated a causal relationship with myocardial infarction." (PMID 41004172, 2025).
FAM13B also shares sentences with these, for which no sentence is quoted: ovarian carcinoma (2 papers); atherosclerosis (1); breast carcinoma (1); ectodermal dysplasia (1); endometrial cancer (1); gestational diabetes mellitus (1); heart disease (1); hepatocellular carcinoma (1); hypopharyngeal squamous cell carcinoma (1); nasopharyngeal carcinoma (1); osteoarthritis (1); osteosarcoma (1); pancreatic cancer (1); virus infection (1).